MMP2 (matrix metallopeptidase 2)
Diseases named in the same sentence as MMP2 in open-access papers (continued):
Sharing a sentence is not in itself a finding about the gene and the disease.
cancer (continued). "MMP-2 and MMP-9 are enzymes that play an important role in basement membrane degradation, which is the first step in the invasion and metastasis of cancer cells." (PMID 34589307, 2021). "The activation of MMP-2 and MMP-9 by HMGA1 and the interaction of these MMPs are reportedly important for the growth and invasion of cancer cells in malignant tumors and those of EVTs in the placenta." (PMID 34072941, 2021). "Intriguingly, HA activates MMP2 and downstream Ras, Rho, PI3K, AKT signaling kinases promoting cancer invasion." (PMID 33809973, 2021). "MMP-2 is an enzyme-degrading type IV collagenase that stimulates the secretion of active MMP-2 by TNF-α and activates processes involved in wound healing and cancer cell invasion." (PMID 33917793, 2021). "Prostaglandin G/H synthase 2 (PTGS2) exhibits the highest degree and regulates 13 types of cancers, followed by HSP90AA1 (degree = 12), EGFR (degree = 12), and MMP2 (degree = 11)." (PMID 34248628, 2021). "Several studies indicated that matrix metalloproteinases (MMPs) such as MMP-2, MMP-7 and MMP-9 play important roles in the migration of ECs and even angiogenesis of various cancers by degrading extracellular matrix (ECM) and releasing various growth factors." (PMID 33573006, 2021). "In the light of these reports, it is understandable that in our study, MB49 cancer cells, throughout their migration from the lumen to the connective tissue, expressed α3β1 integrin, suggesting that it might participate not only in cancer cell attachment but also in MMP-2 activation." (PMID 34199232, 2021). "Snail and Twist are the hallmarks oncogenic transcription factors that downregulate the expression of epithelial marker E-cadherin and upregulate EMT markers fibronectin, c-Myc, cyclin D1, MMP2, and MMP9 in various cancers." (PMID 34711805, 2021). "This was performed through a western blot analysis assay to examine the expression of MMP-2 and MMP-9 in cancer cells after treatment with different nano-formulations." (PMID 34950642, 2021). "MMP2 and MMP9 are recognized as two major enzymes in the degradation of type IV collagen and correlate with an invasive phenotype of cancer cells (Vihinen and Kähäri, 2002)." (PMID 34988077, 2021). "By gelatin zymography, we detected the pro-forms of matrix metalloproteinases MMP-2 and MMP-9 in the conditioned media of MB49 cancer cells cultured in vitro." (PMID 34199232, 2021). "We observed that MMP2 is highly expressed and secreted by fibroblasts and PSCs, whereas MT1-MMP is expressed in both fibroblasts and cancer cells." (PMID 33740019, 2021). "The stromal cell derived leptin is reported to support cancer metastasis in estrogen receptor positive and triple negative breast cancer cells by enhancing EMT via upregulating SERPINE 1, IL-6, MMP-2, SNAI 2, TWIST 1, vimentin and downregulating E-cadherin." (PMID 34588926, 2021). "The results are consistent with other reports suggesting the inactivation of MMP2 and VEGF by EMMPRIN knockdown inhibits cancer migration and invasion." (PMID 34565336, 2021). "As two crucial members of the MMP family, MMP-2 and MMP-9 have also been found to participate in EMT and cancer metastasis." (PMID 34413913, 2021). "MMP-2 and MMP-9 belong to a family of MMPs known to be gelatinases that promote the degradation of type IV collagen in the basement membrane during cancer cell invasion and metastasis." (PMID 33251135, 2020). "In a rat model of breast carcinogenesis application of EGCG overcame MDR to paclitaxel through increased apoptosis, decrease of cancer stem cells, decreased VEGF expression and MMP-2 activity." (PMID 31936346, 2020).
cancer (continued). "MMP-2 and MMP-9 are key molecules in cancer invasion by the proteolytic digestion of the extracellular matrix (ECM) which is the first step to metastasis to help cancer cells to migrate into or out of the vessel walls to metastasize to the distant organs." (PMID 33233701, 2020). "Upon examination of VE-cadherin, ephrin A2, VEGFR2, laminin 5γ2, MMP1, MMP2, MMP9 and MMP14 by the human cancer cells, we made the surprise finding that of the genes investigated, VE-cadherin (CDH5) was the most highly expressed." (PMID 32246008, 2020). "In addition, studies suggested that HIF-1α might also regulate the invasiveness of cancer cells by altering the expression of intermediate filament (vimentin, keratin), extracellular matrix component (fibronectin), and protease (MMP2 and urokinase plasminogen activator receptor)." (PMID 32211041, 2020). "Among various subtypes of MMP proteins, MMP-2 and MMP-9 are frequently found to be related with cancer cell invasion and aggressiveness." (PMID 32155880, 2020). "The levels of various proteinases, such as MMP-2 and MMP-9, are known to be increased during inflammatory diseases and in cancer." (PMID 32774424, 2020). "MMP‐2 and MMP‐9, two important ECM‐degrading enzymes, participate in cancer cell migration and invasion." (PMID 32180962, 2020). "EV-derived TIMP-2, on the other hand, plays a crucial role in the formation of the MT1-MMP-TIMP-2-pro-MMP-2 ternary complex for MMP-2 activation, which is well known for its impact on cancer progression." (PMID 32610589, 2020). "Isoflurane increases the malignant potential of cancer cells through the upregulation of insulin-like growth factor (IGF)-1 and its receptor (IGF-1R), as well as VEGF, angiopoietin-1, MMP-2 and MMP-9." (PMID 32863874, 2020). "Several MMPs such as MT1-MMP, MMP-2, and MMP-9 were found correlated to the stages of cancer cell invasion progression." (PMID 32224968, 2020). "The overexpressions of MMP-2 and MMP-9 are related to the undesirable prognosis of patients with cancer." (PMID 32380783, 2020). "Marimastat inhibits MMP-2, MMP-9, MMP-1, and other MMPs and, it has been reported to inhibit cancer cell migration 3D in vitro at a 30 μM concentration and to inhibit fibroblast mediated collagen hydrogel contraction at a 10 μM concentration." (PMID 32384738, 2020). "It is known that MMP2 and MMP9 can degrade gelatin and Type IV collagen, and break the barriers so that cancer cells can traverse to metastasis." (PMID 33442480, 2020). "RECK is a membrane-anchored MMP inhibitor that negatively regulates activities of MMP-2 and MMP-9, and consequently reduces cancer invasion and metastasis." (PMID 32349289, 2020). "The concentrations of MMP-2 and TIMP-2 measured separately in cancer patients are notable, and the sensitive relationship between MMP-2 and TIMP-2 is also of great interest among scientists and clinicians." (PMID 32751899, 2020). "AIM suppressed TNF-α effects on the NF-κB-regulated proteins involved in cancer cell proliferation (COX-2, and C-myc), invasion, and angiogenesis (MMP-2 and MMP9, ICAM-1 and VEGF)." (PMID 32455624, 2020). "MMP14 and MMP2 both degrade the extracellular matrix especially collagen IV, found in basement membranes, and indeed MMP14 and MMP2 have been shown to promote cancer invasion and metastasis." (PMID 33149188, 2020). "In various types of cancer tissues, IL8 participates in degradation of the extracellular matrix by promoting the expression of MMP-2 and MMP-9 in cancer cells." (PMID 33046030, 2020). "We here demonstrate that, though hypermethylation of certain CpGs in promoter regions of the MMP2, MMP23B, MMP24, MMP25, and MMP28 genes is cancer specific, it lacks independent biological or clinical value, being rather a function from HER2 activation." (PMID 32397602, 2020). "MMP2 and MMP9 play an important role in cancer metastasis by promoting the degradation of extracellular matrix." (PMID 32226772, 2020).
cancer (continued). "Fucoidan inhibits invasion and development of tubules through inhibition of MMP-2, -9 activity and suppressing VEGF expression in cancer cell lines." (PMID 33113890, 2020). "The roles of MMP-2, MMP-9, ICAM-1, and VEGF are well known in the invasion and angiogenesis of cancer." (PMID 32455624, 2020). "As reported, MMP-2 and MMP-9 can regulate the ERK signaling pathway, thereby promoting migration and invasion of cancer cells." (PMID 32670867, 2020). "Expression of genes that played a pivotal role in cancer cell migration, including VEGFA, PLAU, MMP2, MMP9, and MMP14, were reduced in dose-dependent manner of stigmasterol in both cell lines." (PMID 32481565, 2020). "MMP-2 and MMP-9 degrade the extracellular matrix, playing an important role in cancer cell invasion, metastasis, and angiogenesis, which are impacted by EMT formation." (PMID 33062005, 2020). "MMP-2 and MMP-9 were measured by ELISA to examine the inhibitory effects of TAO on extracellular matrix degradation and presumably cancer metastasis." (PMID 33086573, 2020). "We found that MMP2 was decreased in CD147 knockout cells, which was consistent with the previous reports in various types of cancer." (PMID 32727598, 2020). "Gelatinases such as matrix metallopeptidase 2 (MMP2) and MMP9 play crucial roles in cancer cell migration, invasion, and metastasis." (PMID 32708426, 2020). "However, the direct relationship of between 15-LOX and MMP-2 remains unknown in cancer." (PMID 33182324, 2020). "The members of the MMP family like MMP-2 (gelatinase -A) and MMP-9 (gelatinase-B) remain up-regulated in malignant tumors." (PMID 33112542, 2020). "Sulforaphane has been shown to inhibit cancer cell growth and invasiveness by activating ERK signaling, which in turn regulates apoptosis and expression of p21, E-cadherin, MMP2 and CD44v6." (PMID 32443471, 2020). "In our study, T. pratense extract at all the assessed doses (100, 200, and 400 mg/kg) reduced MMP‐2 expression and ultimately inhibited the metastasis of GATA‐3‐positive cancer cells to the brain and lung." (PMID 33133558, 2020). "Preventing CD147 glycosylation can lead to a lower expression of MMP2 and MMP9, which is essential in tissue remodeling and cancer metastasis." (PMID 33374805, 2020). "MMP-2 and MMP-9 expression is known to promote the migration/invasion and metastasis of cancer cells." (PMID 32922544, 2020). "TIMP-1 and TIMP-2 are capable of reducing the expression of MMP-2 and MMP-9 in suppressing metastasis and migration of cancer cells." (PMID 32992587, 2020). "On the other hand, MMP2, which plays roles in degrading the ECM and promoting cell invasion, is also an important component of TLR4-driven cancer metastasis." (PMID 32367494, 2020). "VE-cadherin on tumor cells can activate PI3K through the ERK1/ERK2 pathway which subsequently activates the metalloproteases MMP14 and pro-MMP2, resulting in remodeling of the ECM to enable cancer cells to be reorganized into vessel-like tubes." (PMID 33469537, 2020). "Several studies have revealed that MMP-2 and MMP-9 are correlated with poor prognosis in cancer patients because they are related to interaction of integrins for adhesion and invasion of cancer cells." (PMID 32349276, 2020). "Then, 58 cancer-related targets and 66 KEGG pathways were identified, and PTGS2-, HSP90-, EGFR-, MMP2-, PPARγ-, and GSTP-mediated pathways were predicted to be the antitumor mechanisms of HD-SB." (PMID 32265701, 2020). "It has been known that matrix metalloproteinase-2 (MMP-2) and matrix metalloproteinase-9 (MMP-9) can promote the migration of cancer cells and facilitate extracellular matrix degradation." (PMID 33046984, 2020). "MMP-2 and MMP-9 are enzymes involved in prostatic development and growth, important to cancer progression." (PMID 33013201, 2020). "Transcriptional activation of MMP2 and MMP9 by TGF-β signaling is correlated with the migration and invasion of cancer cells." (PMID 33246423, 2020).
cancer (continued). "For example, MMP2, MMP3, and MMP9 are direct or indirect target genes of FoxO3a in endothelial as well as cancer cells, and FoxO4 upregulated MMP9 expression in smooth muscle cells stimulated by tumor necrosis factor‐α (TNF‐α) by an indirect mechanism." (PMID 32790044, 2020). "Some of the most important genes with promoter DhMRs were BCAR1, which plays crucial roles in metastasis and cell adhesion, and MMP2, which functions in EMT and immune response in multiple cancer types." (PMID 33203436, 2020). "Overexpressed MMP‐2 and MMP‐9 in BC cells facilitate the degradation of type IV collagen, increasing the metastasis and invasion of cancer cells." (PMID 33133558, 2020). "In live cancer, TPX2 inhibited the expression of MMP2 and MMP9 to suppress cell invasion and metastasis." (PMID 33098235, 2020). "Several studies have indicated that transcription factors (e.g., those in the AKT/β-catenin pathways) are involved in regulating the activities of MMP2 and MMP9 and thus cancer cell metastasis." (PMID 33371405, 2020). "The present review discusses the recent findings related to MMPs, particularly MMP-2 and MMP-7, and their involvement in various cancers." (PMID 32751899, 2020). "To elucidate the potential mechanism of this anti-migratory activity, we evaluated the effect of rHct-S3 on the expression level of the matrix metalloproteinases (MMP)-2 and MMP-9, playing a pivotal role in cancer cell invasion and metastasis." (PMID 33348592, 2020). "MMP-2 and MMP-9 are well-known extracellular matrix (ECM)-degrading enzymes that have been reported to play crucial roles in cancer cell metastasis and invasion." (PMID 32225123, 2020). "MMP-2 and MMP-9 provide metastasis of cancer cells into distant organs via degrading matrix collagen and basement membrane." (PMID 32992587, 2020). "Matrix metalloproteinase 2 (MMP2), matrix metalloproteinase 9 (MMP9), snail, and slug are closely related to the migration and invasion of a range of human cancer cells." (PMID 32503225, 2020). "In ER-negative breast cancer, CXCL1 enhances cancer cell migration and invasion through an ERK/MMP2/MMP9 signal pathway." (PMID 33256011, 2020). "AIM suppressed the TNF-α effects on the NF-κB-regulated proteins involved in cancer cell proliferation (COX-2, C-myc), invasion, and angiogenesis (MMP-2, MMP9, ICAM-1, and VEGF)." (PMID 32455624, 2020). "MMP-2 and MMP-9 were overexpressed in many cancers, and this was correlated with increases in cancer cell invasion and numbers/levels of metastases in many types of cancer." (PMID 31772330, 2020). "Matrix metalloproteinase-2 (MMP-2), a family of proteolytic enzymes, exhibits a critical role in carcinoma angiogenesis, progression, metastasis, and invasion through degrading structural components of the extracellular matrix." (PMID 33330618, 2020). "The mRNA levels of VEGF, NFkB, MMP2, MMP9, CDKN2a-p16 and MTNR1a were considerably higher in the carcinomas from PNT rats." (PMID 32499868, 2020). "There are 24 MMPs in mammals, of which MMP2 and MMP9 are found to be overexpressed in many cancer types and promote tumor progression and metastasis." (PMID 31106200, 2019). "Lectin, a glycoprotein isolated from the fruit sap of P. fistulosus, exhibits its potential role against cancer development by decreasing VEGF secretion and inhibiting the expression of MMP2 and MMP9." (PMID 30871059, 2019). "Several proteins are closely related to the migration and invasion of cancers, such as VEGFA, MMP2, and MMP9." (PMID 31631580, 2019). "Previous studies showed that EGR1 downregulates MMP2 and MMP9 by binding directly to their promoter in cancer cells." (PMID 30845713, 2019). "Fundamentally, many other CAF-derived factors, such as matrix metallopeptidase 2 (MMP2), CXCL12, TGF-β, and IL-6, can promote the proliferation and invasion of cancer cells in various tumors." (PMID 31462327, 2019).
cancer (continued). "In line, NGF promotes angiogenesis by TrkA-mediated activation of PI3K and matrix metalloproteinase 2 (MMP2) in breast, ovarian, hepatocellular cancers." (PMID 31812953, 2019). "Here, we showed that expression of MMP-2 and 9 were inhibited by RCFE emphasizing its effect on ECM degradation and invasion of cancer cells." (PMID 31601896, 2019). "Because of the ECM degradation by tumors, MMPs, particularly MMP-2 and MMP-9, play an essential role in the angiogenesis and metastasis of cancer." (PMID 31637006, 2019). "The MMP-2 and MMP-9 received particular attention given that their increased expression appeared related to the malignant potential of several types of cancer, including human gliomas." (PMID 31130597, 2019). "MMP‐2 and MMP‐9 are closely related to the migratory and invasive ability of cancer cells and present in various malignant tumors." (PMID 30653763, 2019). "The STAT3 transcription factor induces the expression of matrix metalloproteinase 2 (MMP-2), MMP-9, and epithelial-mesenchymal transition-related genes in promoting cancer cell invasion and metastasis." (PMID 31885639, 2019). "Several of the genes, including MMP1, MMP2, TIMP1 and HIF1A, are known cancer genes and facilitate stromal invasion." (PMID 31748560, 2019). "Studies have revealed that, both MMP-2 and MMP-9 can degrade type IV collagen and are frequently elevated in human cancer." (PMID 31921634, 2019). "These MMPs (MMP2 and MMP9) are important components for degradation of the ECM during cancer metastasis." (PMID 31263239, 2019). "We also found that combining the compounds markedly downregulated MMP-2, MMP-9, and E-cadherin expression, which correlated with reduced cancer cell migration and invasion." (PMID 30967777, 2019). "Together, these results confirm the contribution of MMP-2 and MMP-9 to cancer angiogenesis through the degradation of ECM components and the activation of pro-angiogenic factors VEGF and TGF-β in diverse cancer tissues." (PMID 31921634, 2019). "Activated CAFs further promote cancer progression via secreting angiogenic cytokines including VEGF, matrix metalloproteinase (MMP)-2, MMP9, basic fibroblast growth factor and transforming growth factor-β." (PMID 31998637, 2019). "The findings of numerous studies emphasized the importance of changes in expression levels of MMP-2 and MMP-9 at different stages of cancer of the head and neck region, including organ and regional staging." (PMID 31223594, 2019). "Among the various MMPs, two members of the MMP family, MMP-2 and MMP-9, are recognized as the most important factors for cancer cell invasion and metastasis in many types of cancers, including PC." (PMID 30621039, 2019). "The activation of MMP-2 is a vital process required by GBM for the ECM to degrade, resulting in the relocation of the cancer to distal parts of the body in a process called metastasis." (PMID 31857956, 2019). "MMP9 and MMP2 are proteases in the MMP family, which, in TNBC tissues, are necessary for extracellular matrix remodeling and cancer cell invasion." (PMID 32047724, 2019). "The aberrant expression of VEGF, MMP‐2, and MMP‐9 was closely related to the growth and metastasis of cancer." (PMID 31762993, 2019). "Inhibition of Notch1 can significantly reduce the binding ability of NF-kappa B to DNA, and the expression and activity of MMP-2 and MMP-9 are also significantly inhibited, thus reducing the metastasis ability of cancer cells." (PMID 30622441, 2019). "MMP-2 and MMP-9 primarily control cancer cell motility, and down-regulation of these proteins was reported across studies to reduce cancer metastasis." (PMID 31011289, 2019). "Invadopodia facilitate the ECM degradation in a variety of cancers through the regulation of various MMPs, primarily MMP-14 (also known as MT1-MMP), MMP-2 and MMP-9." (PMID 30927923, 2019). "Combination activity of MMP2, MMP9 and MMP14 is crucial in initiating localized degradation of the gelatin by invadopodia during cancer metastasis." (PMID 31323836, 2019).